NAA16 (N-alpha-acetyltransferase 16, NatA auxiliary subunit)
Description:
Auxillary subunit of the N-terminal acetyltransferase A (NatA) complex which displays alpha (N-terminal) acetyltransferase activity.
Synonyms: NARG1L; FLJ22054; MGC40612; PRO2435
Tractability: PROTAC: ubiquitination databases record sites on it; its protein half-life has been measured.
Gene: Protein-coding gene on chromosome 13 (41,311,267 to 41,377,035, forward strand). Ensembl gene ENSG00000172766.
Subcellular location (Human Protein Atlas): Cytosol
Gene Ontology:
Molecular function: protein binding; ribosome binding; acetyltransferase activator activity; acetyltransferase activity
Biological process: protein maturation; positive regulation of DNA-templated transcription
Cellular component: cytosol; extracellular exosome; NatA complex; cytoplasm; nucleus; transcription regulator complex
Genetic constraint (gnomAD): Loss-of-function variants: 44 observed, 56.36 expected, observed/expected ratio (o/e) 0.78, 90% interval 0.61 to 1. The upper end of that interval is the gene's LOEUF score, 1, which puts it in group 4 of 6, group 1 being the genes least tolerant of losing a copy. Missense variants: 596 observed, 605.41 expected, observed/expected ratio (o/e) 0.98, 90% interval 0.92 to 1.05. Synonymous variants: 217 observed, 207.41 expected, observed/expected ratio (o/e) 1.05, 90% interval 0.94 to 1.17.
Homologues: Orthologues: chimpanzee NAA16 (99% identical), macaque NAA16 (99% identical), rabbit NAA16 (95% identical), dog NAA16 (95% identical), rat Naa16 (89% identical), mouse Naa16 (88% identical), tropical clawed frog naa16 (82% identical), Drosophila melanogaster Naa15-16 (53% identical), Caenorhabditis elegans hpo-29 (41% identical). Paralogues in human: NAA15 (71% identical), NAA25 (18% identical).
Diseases named in the same sentence as NAA16 in open-access papers:
NAA16 is named in the same sentence as 2 diseases in open-access papers, as found by Europe PMC text mining. Sharing a sentence is not in itself a finding about the gene and the disease. The quoted sentences say what the papers report.
cancer (2 papers, 2020 to 2022). A tumor composed of atypical neoplastic, often pleomorphic cells that invade other tissues. "Within the DepMap genome-wide CRISPR knockout (KO) screen consisting of 739 cell lines of diverse tissue origin, most NATs were essential to all or to a subset of cancer cells, with the exception of NAA60, NAA80, NAA38, NAA11 and NAA16." (PMID 32942614, 2020).
NAA16 also shares sentences with these, for which no sentence is quoted: neurodegenerative disease (1 paper).